PRTN3 (proteinase 3)
Diseases named in the same sentence as PRTN3 in open-access papers (continued):
Sharing a sentence is not in itself a finding about the gene and the disease.
squamous cell vulvar carcinoma (1 paper, 2023). "For instance, the inflammatory response triggered by vulvovaginal microflora may employ PRTN3 in association with the progression of squamous cell vulvar carcinoma (VSCC), which has an aggressive phenotype and may be used for the stratification of patients with this disease." (PMID 37231509, 2023).
staphylococcus aureus infection (1 paper, 2020). An infectious process in which the bacteria Staphylococcus aureus is present. "The Staphylococcus aureus infection pathway as second among the top KEGG pathways differentiating d-fVSCC and progVSCC proteomes, along with the microbicidal PRTN3 protein increase during the disease course, suggest that bacterial infections may be linked to aggressive VSCC phenotypes." (PMID 33374674, 2020).
infection (110 papers, 2006 to 2026). The state of being infected such as from the introduction of a foreign agent such as serum, vaccine, antigenic substance or organism. "PRTN3 is constitutively expressed on neutrophils membrane where a key function is to restore vascular integrity following infection." (PMID 35557837, 2022). "The Mpohi Neu expressed both neutrophil progenitors markers such as Elane, Mpo, and Prtn3 and mature markers such as Camp and Ltf, suggesting that these cells may be newly recruited to the infection foci and undergoing a phenotype transition." (PMID 39985260, 2025). "In addition, genes Prtn3, Elane, and Mpo are functional activation markers of neutrophils involved in inflammation, infection, and tumor invasion." (PMID 37414763, 2023). "At the site of infection, immune cells, such as neutrophils, infiltrate and become activated, releasing neutrophil serine proteases (NSPs), including cathepsin G (CatG), neutrophil elastase (NE), and proteinase 3 (PR3), which promote the mounting of a robust immune response." (PMID 35631327, 2022). "As the infection progresses, this protective layer may be compromised by P. aeruginosa products such as elastase B or host inflammatory factors such as cathepsin G, neutrophil elastase, and proteinase-3, all of which degrade surfactant protein SP-A." (PMID 26090668, 2015). "None of the major neutrophil effector molecules Elastase (ELANE), Proteinase 3 (PRTN3), Cathepsin G (CTSG) and Myeloperoxidase (MPO) changed significantly in response to infection." (PMID 38472281, 2024). "Significant changes in the expression of PRTN3, MPO, and ELANE proteins are very important in the early stage of infection and are significantly related to the severity of the disease." (PMID 37904697, 2023). "Activated neutrophils exocytose neutrophil serine proteases (NSPs), such as neutrophil elastase (NE), proteinase 3 (PR3), cathepsin G (CatG), and neutrophil serine protease 4 (NSP4), at the site of infection." (PMID 36144551, 2022). "Proteinase 3 (PR3) is the most abundant serine protease present in the azurophilic granules of neutrophils and is mostly active in the immune response to infection and is an autoantigen in Wegeners’ disease." (PMID 30154365, 2018). "We found MDM down-regulated PRTN3 6-15-fold (P<0.038) compared to PBMC, WB and MN and that PRTN3 was further down-regulated over 72hr of infection." (PMID 26133770, 2015). "Although c-ANCA (anti-proteinase-3) is highly specific for GPA, the initial trigger may be an infection or other environmental factors, possibly combined with genetic susceptibility." (PMID 38367543, 2024). "The identified up-regulated proteins Myeloperoxidase, Myeloblastin, Neutrophil Elastase, Cathepsin G, and Azurocidin (MPO, PRTN3, ELANE, CTSG, and AZU1) in naso-oropharyngeal swab samples are discussed to highlight the molecular mechanism changes in the site of infection." (PMID 33079950, 2020). "Statistically significant protein alterations of PRTN3, MPO, ELANE, CTSG, and AZU1 dysregulation is important in the early phases of infection and may be targets for anti-SARS-CoV-2 therapeutics." (PMID 33079950, 2020). "This gene encodes a serine protease inhibitor that specifically inhibits neutrophil elastase, cathepsin G, and proteinase-3 present in the neutrophil granules; thus, protecting not only tissues from damage at inflammatory sites during stress or infection, but also the neutrophil itself." (PMID 33746962, 2021). "Furthermore, the hypomethylation found in the gene coding for neutrophil elastase (ELANE) and proteinase 3 (PRTN3) may alter the formation of NETs (neutrophil extracellular traps), which is an earlier mechanism used by neutrophils to fight infection." (PMID 33659006, 2021).
tumor (41 papers, 2007 to 2025). "Further studies analyzing the molecular and cellular mechanisms underlying the effects of PRTN3 on tumor angiogenesis using CRC cell lines and neutrophils and the relationship between PRTN3 and stromal neutrophils, are needed to confirm our results." (PMID 38308214, 2024). "A number of previous studies have implicated that PR1 (a peptide for proteinase-3) is an important tumor antigen for CTL immune response against CML and that specific anti-PR1 T-cells are involved in the elimination of CML cells." (PMID 21857985, 2011). "Activated tumor-associated neutrophils release enzymes, mainly proteinase 3 (encoded by Prtn3), neutrophil elastase (encoded by Elane), and myeloperoxidase (coded by Mpo), destroying surrounding tissues, which may lead to tumor invasion." (PMID 37414763, 2023). "Furthermore, PRTN3 expression in tumor tissue is associated with poor prognosis in some carcinomas." (PMID 38308214, 2024). "PRTN3 is involved in neutrophil differentiation and proliferation, inflammation, and vasculitis, as well as in the invasion of tumor cells and endothelial cells through the activation of matrix metalloproteinases." (PMID 38308214, 2024). "In short, IHC analysis showed that in the primary tumor, PRTN3 was expressed in both cancer and stromal cells." (PMID 38308214, 2024). "PRTN3 promotes tumor growth via multiple oncogenic factors and the PI3K/AKT and P38/ERK signaling pathways." (PMID 37231509, 2023). "To further validate the effects of PRTN3 in the HCC milieu and the interaction between KCs and tumor cells induced by PRTN3, we isolated human KCs from normal liver tissues." (PMID 37231509, 2023). "The interaction of neutrophil Cathepsin G with tumor cell RAGE is required for neutrophil cytotoxicity to kill tumor cell, while neutrophil proteinase 3 interacts with tumor cell RAGE to promote the bone metastasis of prostate cancer." (PMID 33101283, 2020). "Combined efforts of neutrophil elastase, cathepsin G and proteinase 3 activate progelatinase A, that degrades the extracellular matrix followed by the subsequent release of growth factors, tumor-cell invasion and angiogenesis in the TME." (PMID 32733461, 2020). "This might be related to the recognition of tumor antigens [epitopes like Wilms tumor 1(WT-1), proteinase-3, cancer-testis antigens (CTAs)] by specific anti-tumoral CD8+ T cells that target clonal hematopoietic cells and inhibit disease evolution." (PMID 40227622, 2025). "PRTN3 expression in tumor and stromal cells was evaluated immunohistochemically." (PMID 38308214, 2024). "The PRTN3-related immune response could participate in tumor progression, which was supported by several studies." (PMID 37231509, 2023). "Here, we first explored the direct tumor-promoting roles of PRTN3 expressed in KCs and hepatocytes." (PMID 37231509, 2023). "Additionally, neutrophils promote tumor motility, migration and invasion via the release of neutrophil elastase, cathepsin G, proteinase 3, MMP8 and MMP9." (PMID 35682709, 2022). "Mechanically, tumor-secreted cathepsin C promoted the maturation and release of IL-1β in pulmonary neutrophils by activating the neutrophils membrane localization proteinase 3 (PR3) through enzyme digestion." (PMID 35719975, 2022). "Inflammatory proteases from neutrophils (proteinase 3, elastase, and cathepsin G) and mast cells within the tumor microenvironment (chymase, tryptase, and granzyme B) can process full-length IL-33 into shorter mature forms (18–21 kDa), with a 10- to 30-fold higher amount of activity." (PMID 35409061, 2022). "PMNs help the degradation of extraneous materials by elastase, proteinase 3 and cathespins stored in them, which may have resulted in profuse biomatrix digestion observed in DC scaffolds in normal mice or empty biomatrix in tumor mice." (PMID 27223090, 2016). "PRTN3 promotes the activation of matrix metalloproteinases (MMP)-2, which are involved in angiogenesis and tumor invasion." (PMID 38308214, 2024).
tumor (continued). "After overexpression of PRTN3 in HCC cells under heat stress, multiple oncogenic factors and signaling pathways are activated and contribute to tumor growth." (PMID 37231509, 2023). "Neutrophils can release neutrophil elastase, matrix metalloprotease 8 (MMP8), matrix metalloprotease 9 (MMP9), vascular endothelial growth factor (VEGF), cathepsin G and proteinase-3 to degrade the extracellular matrix (ECM) and promote tumor invasion." (PMID 33526991, 2021). "Other authors have linked carcinogenesis to AAT degradation by matrix metalloproteinases activated by neutrophil elastase, cathepsin G, and proteinase-3, ultimately resulting in the production of COOH-terminal fragments, which boosts tumor growth in vivo." (PMID 24886427, 2014). "The proteinase 3 inhibitor sivelestat diminishes the tumor-secreted protease cathepsin C-induced activation of PR3-IL-1β-NF-κB-mediated recruitment of neutrophils and NETosis, thus further inhibiting NET-dependent colonization of tumor cells." (PMID 38023616, 2023). "In addition, transcripts of antimicrobial response effectors were less abundant in tumor tissue, with BPI, MPO and PRTN3 levels being significantly lower compared with those found in healthy tissue (p = 0.0133, p = 0.002 and p = 0.0022, respectively)." (PMID 24421902, 2014).
cancer (30 papers, 2006 to 2025). A tumor composed of atypical neoplastic, often pleomorphic cells that invade other tissues. "To investigate the association between PRTN3 and cancer progression promoted by RFA in patients with HCC, we analyzed the predictive power of PRTN3 in the OS of early recurrent HCC following RFA." (PMID 37231509, 2023). "In this study, the proportion of PRTN3-positive cancer cells and macrophages was associated with a shorter time to progression in patients with VSCC)." (PMID 37118737, 2023). "There have been documented associations between PRTN3 protein and cancer progression." (PMID 40028338, 2025). "Our findings revealed that the expression of PRTN3 protein was significantly higher in LUAD tissues compared to para-carcinoma and NC tissues (P < 0.0001)." (PMID 40028338, 2025). "Immunohistochemical analysis revealed higher expression of PRTN3 in cancer tissues of HCC with early recurrence after RFA than in tissues from before RFA (p = 0.0174)." (PMID 37231509, 2023). "Patients with higher numbers of PRTN3-positive cancer cells in the tumors had a significantly shorter time to progression than those with low numbers of these cells." (PMID 33374674, 2020). "Ingenuity pathway analysis revealed that differentially methylated CpG sites were annotated to genes involved in ‘cell cycling’ (e.g. NDRG1, NEDD1, and MAD1L1), ‘inflammatory diseases’ (e.g. PRTN3), and ‘cancer’ (PCDHA6, MUC4, and ATP2C2)." (PMID 28754985, 2017). "Our functional experiments also demonstrated that PRTN3 may drive cancer migration and metastasis via interactions between heat stress-treated HCC cells and KCs, which are liver-resident immune cells." (PMID 37231509, 2023). "Notably, we detected several critical regulating proteins associated with cancer processes, such as CAMP, MMP9, the S100 family (100A8, S100A9, S100A12), and PRTN3, among the proteins with the most significant increases." (PMID 37231509, 2023). "Notably, PRTN3 has been found to be overexpressed in early-stage cancers." (PMID 40028338, 2025). "However, the relationship between anti-PRTN3 autoantibody and cancer remains largely unexplored." (PMID 40028338, 2025). "PRTN3, ELANE, CTSG and MMP9 are the serine proteases released by the activated neutrophils and have been reported to degrade ECM proteins and promote cancer cell invasion." (PMID 36686780, 2022). "We identified several novel candidate genes (e.g., ICAM3, CCL16, PDE3A, and PRTN3) and showed that ICAM3 mediates cancer cell stemness as well as cancer-related inflammation via Src/PI3K/AKT signaling." (PMID 33500726, 2021). "The neutrophil degranulation complex was defined by the terms antimicrobial peptides (R-HAS-6803157), neutrophil degranulation (R-HSA-6798695), response to yeast (GO:0001878), and transcriptional misregulation in cancer (KEGG:05202); it included the proteins ELANE, H3-5, MPO, LYZ, and PRTN3." (PMID 39997396, 2025). "Furthermore, we observed significantly increased expression levels of anti-PRTN3 IgG and IgM autoantibodies in the early-stage of LUAD, which aligns with the characteristic appearance of autoantibodies during the early-stages of cancer." (PMID 40028338, 2025). "Among cancer and precancerous lesions glycoproteins, we further highlight seven glycoproteins found in high-grade dysplasia as well as cancer (IGHG1, CPA2, MYH2, AZU1, PRTN3, CA1, SMPDL3B), holding potential for non-invasive detection of aggressive traits." (PMID 38612533, 2024). "While our study primarily focuses on mCRC, these preliminary findings suggest that the role of PRTN3 in angiogenesis and the chemotherapy response may extent to the patients with stage I-III CRC, other cancer types, and other drugs targeting vascularization." (PMID 38308214, 2024). "In general, the observed percentage of PRTN3-positive cells was lower among cancer cells than among the infiltrating non-neoplastic cells." (PMID 33374674, 2020).
cancer (continued). "Serum PRTN3 levels were not correlated with the degree of PRTN3 expression in cancer cells." (PMID 38308214, 2024).
inflammation (14 papers, 2009 to 2025). Aberrant reaction of the microcirculation characterized by movement of fluid and leukocytes from the blood into extravascular tissues. "In a murine E. coli lung inflammation model, it has been demonstrated that 15-epi-LAX4 and 17-epi-RvD1 signal through the ALX/FPR2 receptor on PMN to inhibit Toll-like receptor 9-mediated release of neutrophil elastase (NE) and proteinase 3 (PR3)." (PMID 36742292, 2023).
bacterial infections (8 papers, 2015 to 2025). "Its expression has been found increased in patients with several bacterial infections, associated with the neutrophil surface proteinase 3 (PR3) expression." (PMID 40149670, 2025). "Genetic defects in alpha-1 antitrypsin, proteinase 3 gene, major history compatible complex class II gene, bacterial infections (staphylococci), virus (hepatitis C, cytomegalovirus, and Epstein-Barr virus), and medications like hydralazine, allopurinol, and phenytoin are other risk factors for GPA." (PMID 36337814, 2022). "Bacterial infections lead to neutrophil activation triggering their antimicrobial functions, involving neutrophil phagolysosomes and neutrophil extracellular traps (NETs) that encompass multiple proteases, including PRTN3." (PMID 33374674, 2020).
infectious disease (7 papers, 2012 to 2025). A disorder directly resulting from the presence and activity of a microbial, viral, or parasitic agent in humans. "In the absence of classic IE manifestations, such findings may point the clinician toward an auto-immune instead of an infectious disease, in particular when antineutrophil cytoplasmic antibodies (ANCAs) directed against proteinase-3 (PR3) or myeloperoxidase (MPO) are detected." (PMID 35732985, 2022).
hematologic disorder (2 papers, 2019 to 2022). A disease involving the hematopoietic system. "This is especially the case for many hematologic malignancies (HM), as demonstrated by a promising target of immune-mediated antitumour responses: PR1, a nine-amino acid-long HLA-A2-restricted peptide, which derives from proteinase 3 (PR3)." (PMID 31198793, 2019).
CNS tumors (1 paper, 2021). "Early studies on the capacity of NET-related proteins such as elastase, proteinase-3, and cathepsin G to invade CNS tumors preliminarily showed traces of NETs in CNS tumors." (PMID 34336122, 2021).
PRTN3 also shares sentences with these, for which no sentence is quoted: rheumatoid arthritis (88 papers); eosinophilic granulomatosis with polyangiitis (41); systemic lupus erythematosus (28); renal disease (21); inflammatory bowel disease (12); renal failure (11); melanoma (10); scleritis (10); End-stage renal disease (9); membranous nephropathy (9); nasal polyps (9); connective tissue disease (8); Goodpasture's syndrome (8); Hypertension (8); interstitial lung disease (8); myositis (8); pulmonary fibrosis (8); endocarditis (7); Pulmonary hemorrhage (7); sinusitis (7); kidney damage (6); leukocytoclastic vasculitis (6); peripheral neuropathy (6); rheumatic diseases (6); cystic fibrosis (5); Hepatitis (5); hepatitis C (5); neutropenia (5); primary biliary cholangitis (5); rapidly progressive glomerulonephritis (5).
A further 267 diseases each share a sentence with PRTN3 in 5 papers or fewer.